TTR (transthyretin)
Diseases named in the same sentence as TTR in open-access papers (continued):
Sharing a sentence is not in itself a finding about the gene and the disease.
amyloidosis (continued). "In a Japanese observational study, 22 patients with TTR Val30Met mutation and 3 with Tir114Cis mutation (Tyr114Cys) were observed and it was found that 3 (12%) had glaucoma, 3 (12%) had amyloid deposits on the pupil edge, and 1 (4%) developed vitreous opacities." (PMID 26558262, 2015). "TTR is associated with at least two amyloidoses: senile systemic amyloidosis (SSA) and FAP." (PMID 25086037, 2014). "However, the fact that most of the known mutations in the TTR gene have important implications for amyloidosis suggests that there are aspects of TTR structure that are not fully understood." (PMID 25485123, 2014). "Massive deposits, as seen in lysozyme-associated amyloidosis or certain forms of TTR-associated amyloidosis, could be deleterious due to the volume–or to mechanical effects on heart movements, for example." (PMID 23390551, 2013). "It is important to investigate the mechanism behind SAP-TTR interaction in greater detail, since SAP may have an important modulatory role in TTR-associated amyloidosis." (PMID 23390551, 2013). "TTR misfolding and aggregation are associated with human amyloid diseases." (PMID 24121323, 2013). "More than 100 mutations in TTR associated with amyloidosis have been described." (PMID 23853716, 2013). "Autonomic neuropathy may also affect gut function, which was distinguished in GI symptoms caused by mutant transthyretin amyloidosis." (PMID 23617890, 2013). "FAP type I is the most common of the TTR-associated amyloidoses." (PMID 24358189, 2013). "Defects in this gene cause amyloidosis transthyretin-related disorder (AMYL-TTR)." (PMID 23028713, 2012). "Familial amyloidosis in humans could be due to mutations in fibrinogen, lysozyme, apolipoprotein AI, and transthyretin (with ATTR as amyloid protein)." (PMID 22577608, 2012). "Transthyretin is one of the human proteins known to be associated with local amyloidosis." (PMID 20498702, 2010). "Protein misfolding and aggregation, with formation of amyloidogenic aggregates and amyloid filaments have become of increasing interest due to their involvement in many debilitating disorders such as Alzheimer's disease, Parkinson's disease and TTR-associated amyloidoses." (PMID 21179560, 2010). "The compounds presented here constitute a new class of TTR inhibitors that may hold promise in treating amyloid diseases associated with TTR misfolding." (PMID 19621084, 2009). "The protein TTR occurs in over 100 variants and most of them cause amyloidosis." (PMID 19662213, 2007). "However, transthyretin amyloidosis (ATTR) can also involve the small bowel and cause CIPO." (PMID 40376135, 2025). "Notably, we also observed strong interactions between LILRB2 and LILRB5 receptors and transthyretin (TTR) oligomers, another well-characterized amyloid protein implicated in transthyretin amyloidosis, suggesting a broader role for amyloid–LILRB interactions in amyloid-related diseases." (PMID 41233352, 2025). "Notably, subpial TTR amyloid deposits are associated with astrocytosis, highlighting that astrocytic activation and damage are crucial features of ATTRv pathology and may significantly contribute to the observed elevation in serum GFAP concentrations." (PMID 40232501, 2025). "In ATTR amyloidosis, the TTR tetramers are destabilized, either due to structural changes resulting from genetic mutations (in ATTRv) or yet unknown age-related factors (in ATTRwt amyloidosis)." (PMID 40649158, 2025). "The identification of the first case of transthyretin amyloidosis diagnosed at Manuel Ygnacio Monteros Hospital with the pSer43Asn variant has motivated us to carry out a descriptive study of those index cases identified as carriers of the mutant transthyretin gene." (PMID 39449414, 2024).
amyloidosis (continued). "The TTR Val30Met variant is one of the most prevalent variants worldwide (possibly only trumped by the Val122Ile variant and its occurrence is in 3–4% of African Americans) and is responsible for the high prevalence of ATTRv amyloidosis in endemic regions such as Portugal, Sweden, and Japan." (PMID 38907862, 2024). "Additionally, wild-type transthyretin amyloidosis (ATTRwt) might be a potential mechanism underlying the association between low transthyretin concentrations and increased risk of mortality or readmission." (PMID 39478501, 2024). "Anyone suspected to have amyloidosis should receive appropriate testing for a definitive diagnosis to catch the disease process and offer early treatment, as exciting research is emerging showing transthyretin stabilizers to have a reduction in all-cause mortality." (PMID 37485202, 2023). "TTRV122I and TTRV30M, the most prevalent amyloidogenic TTR mutations globally, are incompletely penetrant in some families and may not cause disease even in individuals homozygous for the pathogenic allele, while wild-type ATTR amyloidosis is exclusively a disease of late middle age and beyond." (PMID 34876572, 2021). "Indeed, it was previously reported that different TTR variants might experience differential structural deformation pathways that could be responsible for amyloidosis or cytotoxic activities." (PMID 33922648, 2021). "In addition, we will also test these compounds in different TTR amyloidogenic variants and other amyloid systems, such as the amyloid-beta peptide and lysozyme, which are implicated in Alzheimer’s disease and lysozyme amyloidosis, respectively." (PMID 35008816, 2021). "R34 and K35 are two positively charged residues residing at the C-terminus of TTR β-strand B. We have shown that, in vitro, these sequentially adjacent positive charges contribute to protect TTR against aggregation, which may justify why the loss of one of these charges results in amyloidosis." (PMID 34343569, 2021). "Thus, the first siRNA-based drug (Patisiran) has recently obtained the FDA approval to silence the transthyretin (TTR) mRNA (via RNA-interference by binding its 3′UTR) which caused a rare transthyretin-mediated amyloidosis polyneuropathy originated by the deposit of TTR-protein in tissues." (PMID 32009226, 2020). "Furthermore, using a NGS panel of 311 genes related to cardiomyopathies/channelopathies, a disease-causing variant was identified in 10 athletes: 6 HCM, 1 Fabry disease; 1 LVNC, 1 LQTS and a pathogenic polymorphism in the transthyretin gene, associated with wild-type transthyretin amyloidosis." (PMID 32932687, 2020). "Therefore, an individual’s TTR amyloidosis risk could be assessed by measuring the individual’s serum TTR concentration and the stability of their TTR tetramer with respect to the monomer." (PMID 33203794, 2020). "In addition, the binding of MT-3 to the TTR monomer may cause disturbances in the formation of amyloid, being the main cause of systemic amyloidosis and familial amyloid polyneuropathy, which involves mutated variants of TTR." (PMID 33256250, 2020). "Amyloid cardiomyopathy caused by wild-type transthyretin (ATTRwt) amyloidosis may be difficult to distinguish clinically from that caused by AL amyloidosis, though features such as age or a discordance between the extent of myocardial thickening and the extent of symptoms may serve as clues." (PMID 30837451, 2019). "The spectrum of systemic TTR amyloidosis comprises the many very rare hereditary forms caused by different mutations, the cardiac amyloidosis caused by the V122I variant in individuals of African origin and cardiac amyloidosis, mostly in elderly men, caused by WT TTR." (PMID 30018138, 2018). "TTR (transthyretin) gene could be a possible candidate for lumbosacral stenosis in Labrador retrievers based on previous human studies that have reported an association between human lumbar spinal stenosis and transthyretin protein amyloidosis." (PMID 29085643, 2017).
amyloidosis (continued). "The mechanisms underlying transthyretin-related amyloidosis in vivo remain unclear." (PMID 26286619, 2015). "Proteostasis may thus be as important as point mutations in transthyretin amyloidosis." (PMID 26147092, 2015). "However, in transthyretin (ATTR) amyloidosis, the underlying molecular mechanisms are largely unknown." (PMID 26199771, 2015). "Recent clinical trials of encapsulated RNAi in lipid nanoparticle for transthyretin amyloidosis, caused by the deposition of hepatocyte-derived transthyretin amyloid in peripheral nerves and the heart, have demonstrated safety and efficacy with respect to lowering transthyretin levels." (PMID 26006249, 2015). "The positive predictive value (PPV) for TTR amyloidosis reached 92%, while Friedrich’s ataxia was correctly identified in all cases (PPV = 100%)." (PMID 41574038, 2026). "Wild-type transthyretin amyloidosis (ATTRwt-CA) accounted for the majority of cases, representing 76% (95% CI, 57%-89%) of CA diagnoses and a pooled prevalence of 11% among screened populations." (PMID 41646327, 2026). "The main subtypes are light-chain (AL) and transthyretin (ATTR) amyloidosis, while AA and isolated atrial amyloidosis (IAA) are less common." (PMID 41596468, 2026). "Bone scintigraphy using technetium-99 m-labelled phosphonates is a sensitive, easy-to-perform, highly cost-efficient, and widely available method of imaging cardiac transthyretin (ATTR) amyloidosis." (PMID 41037105, 2026). "The most frequently implicated proteins in amyloidosis include immunoglobulin Free Light Chains (FLC), related to AL amyloidosis, and transthyretin (TTR), which is responsible for ATTR amyloidosis." (PMID 41756701, 2026). "Transthyretin (ATTR) amyloidosis results from the deposition of misfolded transthyretin, a tetrameric protein synthesized in the liver responsible for transporting thyroid hormone and retinol." (PMID 41596468, 2026). "Methods: sNfL was measured retrospectively in 10 pathogenic transthyretin gene variant (TTRv) carriers and 28 patients with ATTRv amyloidosis." (PMID 41827277, 2026). "Although small molecular weight drugs can stabilize TTR preventing its aggregation, molecular mechanisms of transthyretin amyloidosis remain poorly understood." (PMID 41520423, 2026). "The main types with cardiac involvement are light-chain (AL) amyloidosis and transthyretin (ATTR) amyloidosis, the latter occurring in both hereditary (ATTRv) and wild-type (ATTRwt) forms." (PMID 41590246, 2026). "It targets TTR and is delivered in vivo to knockout the TTR gene and ameliorate transthyretin amyloidosis." (PMID 41141388, 2026). "The treatment of TTR amyloidosis has been revolutionized by the introduction of TTR tetramer stabilizers such as tafamidis and acoramidis as well as TTR gene silencers such as patisiran, vutrisiran, and eplontersen." (PMID 40985278, 2026). "The disease results from the misfolding of precursor proteins, primarily immunoglobulin light chains (in light chain (AL) amyloidosis) or transthyretin (in transthyretin (ATTR) amyloidosis), into insoluble fibrils that deposit in myocardial tissue." (PMID 41659097, 2026). "The first described a woman with symptomatic hereditary transthyretin‐related amyloidosis who received patisiran, a siRNA silencing transthyretin (TTR) gene, during the third week of amenorrhea." (PMID 41358055, 2026). "Wild-type transthyretin amyloidosis (ATTR-wt) is the most common type affecting subjects above 60 years old." (PMID 42123347, 2026). "Data from global studies like the Transthyretin Amyloidosis Outcomes Survey (THAOS) confirms the presence of the disease in these regions, indicating that ATTR amyloidosis is indeed a global concern." (PMID 39819351, 2025). "Transthyretin (ATTR) amyloidosis is a systemic disorder characterized by the misfolding of transthyretin protein and deposition of insoluble fibrils in body tissues, with a marked predilection for cardiac involvement." (PMID 41517554, 2025).
amyloidosis (continued). "ATTR cardiomyopathy is a form of amyloidosis where the transthyretin (TTR) protein forms misfolded fibrils that deposit in the heart." (PMID 41295360, 2025). "The inclusion criteria focused on studies discussing multidisciplinary clinical environments for amyloidosis care, particularly light-chain (AL) and transthyretin amyloidosis (TTR)." (PMID 40114122, 2025). "There are currently over 30 known proteins that can lead to CA and the most common forms are transthyretin (ATTR-CA) and immunoglobulin light chain (AL-CA) amyloidosis." (PMID 40675021, 2025). "Clinical validation of siRNA therapeutics was significantly advanced by the approval of Patisiran, which targets transthyretin mRNA to treat hereditary transthyretin-mediated amyloidosis." (PMID 41211454, 2025). "In the context of TTR amyloidosis, siRNAtherapeutics target the TTR gene, which codes for the TTR protein." (PMID 41524065, 2025). "Background and aims: Amyloid Transthyretin (ATTR) amyloidosis is a debilitating and often misdiagnosed condition, characterized by the accumulation of transthyretin amyloid fibrils in various organs and tissues." (PMID 40542608, 2025). "This activation follows the progressive stages of TTR-amyloidosis in the CNS, which increase in extent as the disease progresses." (PMID 40232501, 2025). "The first approved siRNA drug, Patisiran, which is formulated into LNPs, effectively treats hereditary transthyretin-mediated amyloidosis, and its liver-specific delivery system also shows potential for liver cancer treatment." (PMID 39776807, 2025). "Although regional myocardial deformation analysis shows apical sparing phenomenon in both the amyloidosis subtypes, TTR‐CM had significantly a lower basal LS and higher RASI, when compared with AL‐CM (0.92 ± 0.29 vs. 1.46 ± 0.53, p = 0.001)." (PMID 39873364, 2025). "Transthyretin (TTR) amyloidosis occurs due to the accumulation of TTR amyloid, which is produced by hepatocytes." (PMID 40927763, 2025). "At this time, we are now fortunate to have a multitude of therapies to choose from for treatment of those afflicted with TTR amyloidosis with cardiac involvement, including both stabilizers and silencer therapies, both of which are approved in the USA." (PMID 40943848, 2025). "Emerging data suggest a potential but under‐reported role of ATTR amyloidosis (transthyretin‐related deposits) in tracheobronchial manifestations, warranting further investigation." (PMID 40231310, 2025). "Liver transplantation is performed in patients with hereditary transthyretin amyloidosis to remove the source of abnormal transthyretin production to slow disease progression." (PMID 40406766, 2025). "Genomic manipulation provides a powerful opportunity to understand how iPSCs derived from patients with known amyloid mutations, especially TTR-ACM, can help study amyloid disease phenotypes in an isogenic background." (PMID 41295360, 2025). "Considering the multifaceted impact of transthyretin amyloidosis, significant correlations were observed between key CPET parameters, [99mTc]-DPD retention index, and various clinical, laboratory, and imaging metrics." (PMID 40364030, 2025). "99mTc‐pyrophosphate scintigraphy scan showed cardiac uptake consistent with transthyretin amyloidosis, and genetic testing confirmed wild‐type disease." (PMID 41321348, 2025). "We detail their mechanisms of action, delivery systems—with a focus on lipid nanoparticles and N-acetylgalactosamine (GalNAc) conjugates—and clinical efficacy in treating conditions such as transthyretin (TTR) amyloidosis." (PMID 40943573, 2025). "Amyloid transthyretin amyloidosis is a debilitating and life-threatening disease caused by the misfolding and aggregation of mutated transthyretin (TTR) protein, which deposits in multiple organs and tissues, leading to progressive damage and dysfunction." (PMID 40433205, 2025).
amyloidosis (continued). "The two main subtypes are light-chain (AL-CA) and transthyretin (ATTR-CA) CA amyloidosis, with the latter being further classified into hereditary (hATTR) and wild-type (wtATTR) forms." (PMID 40283481, 2025). "In a retrospective study, involving 103 patients, 16.5% of them had CKD at the time of TTR amyloidosis diagnosis, while 16.1% had proteinuria." (PMID 40755967, 2025). "The instability of TTR tetramer was also thought to be a key step in the formation of ATTR related amyloidosis, which has promoted the discovery and development of TTR tetramer stabilizers." (PMID 40765557, 2025). "Patients with ATTR‐CM receiving transthyretin stabilizer therapy at the West German Amyloidosis Center (01/2018–12/2023) were included." (PMID 40296427, 2025). "In summary, TTR genetic testing is an indispensable tool in the comprehensive management of ATTRv amyloidosis, providing critical information for diagnosis, treatment, and familial risk assessment." (PMID 40804349, 2025). "ATTR amyloidosis is caused by inherited TTR gene variants that encode unstable protein in hereditary ATTR (ATTRv, v for variant) amyloidosis or is associated with aging in wild-type ATTR (ATTRwt) amyloidosis." (PMID 40555140, 2025). "We performed amyloid typing using liquid chromatography with tandem mass spectrometry (using methods described previously), which demonstrated ATTR (transthyretin)‐type amyloidosis." (PMID 41262227, 2025). "Biochemically, cardiac amyloid deposits often contain both full-length TTR and C-terminal TTR fragments, with cleavage at positions like 48, 49, or 81 enhancing amyloidogenicity under physiological shear stress." (PMID 41295360, 2025). "Cystatin C, with an AmyloGram score of just 0.73, and transthyretin (0.74) are directly responsible for two well-known amyloidoses." (PMID 41099342, 2025). "INTRODUCTION: In wild-type transthyretin amyloidosis (ATTRwt), the deposition of transthyretin in the myocardium leads to progressive heart failure." (PMID 41116186, 2025). "Here, we present a patient with anti-IgLON5 disease who additionally suffered from transthyretin (ATTR)-amyloidosis and died after cardiac arrest." (PMID 41008281, 2025). "Four of the studies discussed TTR amyloidosis only (57%); three of the studies discussed both AL and TTR amyloidosis (43%)." (PMID 40114122, 2025). "We report a case of wild‐type transthyretin amyloidosis (ATTRwt) in a 91‐year‐old female who developed alveolar hypoventilation despite improvement in heart failure." (PMID 41321348, 2025). "Transthyretin (ATTR) amyloidosis is a rare disease characterized by the deposition of amyloids in organ tissues throughout the body, particularly affecting the cardiac and/or nervous systems, and causing progressive damage over time if untreated." (PMID 40299173, 2025). "In younger patients with biventricular thickening and restrictive physiology, genetic transthyretin (TTR) amyloidosis, Fabry disease, and hypertrophic cardiomyopathy with a restrictive phenotype should all be included in the differential." (PMID 41010872, 2025). "Right ventricular (RV) biopsy and multi-phase skeletal scintigraphy diagnosed transthyretin amyloidosis with cardiac involvement." (PMID 39963604, 2025). "The prospects for developing small molecules as kinetic stabilisers of the TTR tetramer and thus as amyloidosis inhibitors was recognised more than twenty years ago with structure-based drug design ventures published." (PMID 40367241, 2025). "In recent years, the therapeutic outlook for TTR amyloidosis has significantly improved with the emergence of several specific amyloidosis treatments." (PMID 40526695, 2025). "Inotersen was the first ASO therapy evaluated in the NEURO-TTR trial (ClinicalTrials.gov Identifier: NCT01737398), a pivotal phase 3 study involving 172 patients with variant transthyretin amyloidosis and polyneuropathy (ATTRv-PN)." (PMID 40056371, 2025).